MYC (MYC proto-oncogene, bHLH transcription factor)
Diseases named in the same sentence as MYC in open-access papers (continued):
Sharing a sentence is not in itself a finding about the gene and the disease.
cancer (continued). "Moreover, in 33 different human cancers, expression of both MYC and TWIST1 predict survival, expression of CCL2/IL13 and M2-like TAM infiltration." (PMID 31933479, 2020). "In addition, MYC signaling is also reported to regulate metabolism 41-43 and stemness 44 of cancer cells." (PMID 32685003, 2020). "Moreover, the transcription factor MYC has been suggested as a positive regulator of EZH2 by different mechanisms in several types of cancers." (PMID 33014831, 2020). "Moreover, FAM83H stimulates the proliferation of cancer cells by inducing cell cycle progression in conjunction with MYC and canonical Wnt pathways." (PMID 32460791, 2020). "Abundant evidence has indicted supraphysiological MYC levels in cancer." (PMID 32715994, 2020). "Also, a number of MYC synthetic lethal pathways have been explored for targeting MYC-driven cancers." (PMID 33251216, 2020). "As discussed, MYC amplification is common among many cancer types." (PMID 33322239, 2020). "Disruption of SEs may therefore selectively affect MYC and other oncogenic genes in cancer cells and genes regulating fibrosis in CAFs." (PMID 33168807, 2020). "MYC is one of the proto-oncogenes contributing to tumorigenesis in many human cancers." (PMID 32411526, 2020). "WNT signaling enhances MYC expression in cancer cells to increase the rate of cell proliferation." (PMID 32158925, 2020). "Besides, correlation analysis showed MYC, AKT1 mRNA expression and glycolysis score were positive correlated across a variety of cancers ranging from r = 0.10 to 0.57 for MYC and r = 0.15 to 0.50 for AKT1 (p < 0.05)." (PMID 32635458, 2020). "The MYC gene is one of the most highly amplified oncogenes among many human cancers." (PMID 32098783, 2020). "This is exemplified in the enrichment of cancer-associated metabolic and proliferative events, such as integrin signaling, IF1/2-mediated events, Syndecan-2-mediated signaling and uPA/uPAR-mediated signaling, and MYC and associated transcription factors." (PMID 32885042, 2020). "Moreover, the circadian clock is strongly damped or even abrogated by oncogenes such as MYC yet MYC-driven cancer cells retain high intra-generational correlations." (PMID 31971512, 2020). "A recent study has revealed that MYC alterations are mutually exclusive with PIK3CA, PTEN, APC, or BRAF alterations, suggesting MYC amplification as a distinct driver mutation in the cancer genome." (PMID 32235890, 2020). "In addition, FAM83H had cooperative roles with MYC and Wnt/β-catenin pathways in cancer progression." (PMID 32460791, 2020). "Hence it is of paramount importance to understand the functional regulators of MYC and its targets and their interplay in contributing to the aggressiveness of MYC dependent cancers." (PMID 31932624, 2020). "Moreover, RAS activates a signaling cascade that leads to MYC protein stabilization in cancer cells." (PMID 33081056, 2020). "MYC is a well-known oncogene and amplified in a wide array of human cancers." (PMID 32405341, 2020). "MYC genes are highly deregulated proto-oncogenes in human cancer." (PMID 32724061, 2020). "These alterations in NFKBIA and MYC are shown to potentially be prognostic in some cancer types." (PMID 32099096, 2020). "Additionally, we showed that CDK7 inhibition reactivated immunity by suppressing p38α/MYC/PD-L1 and sensitized cancer cells to anti-PD1 therapy in vivo, which indicated CDK7 as an attractive target for epigenetic therapy of NSCLC." (PMID 32690037, 2020). "MYC is a transcription factor that acts as a master regulator of gene expression in cancer." (PMID 31638140, 2020). "This suggests that while c-MYC expression is mostly cytoplasmic in cancer, either nuclear or cytoplasmic expression of c-MYC may contribute to tumorigenesis." (PMID 32019273, 2020). "Taken together, these data reinforce the hypothesis of a positive feedback loop between MYC and IRE1α‐XBP1s pathway, which may be a critical driver of various MYC‐dependent cancers." (PMID 32310340, 2020).
cancer (continued). "This suggests different mechanisms of PVT1 and MYC cooperation in different cancers." (PMID 32117705, 2020). "MYC is an indispensable factor for cell growth and proliferation in normal tissues, but at the same time, it is one of the most well-known proto-oncogenes, with high amplification in various carcinomas." (PMID 32411526, 2020). "MYC signaling pathway is essential for cancer stem cell self-renewal and cell survival." (PMID 31666930, 2019). "Thus, PGG induced G1 cell cycle arrest and apoptosis in cancer cells can also be explained by MYC inhibition." (PMID 30760754, 2019). "Thus, PCGEM1 affects the metabolic state of cancer cells by enhancing MYC occupancy at the promoters of several metabolic genes." (PMID 30451365, 2019). "Moreover, the MycER chimeric protein system, which can be applied to cell-line and mouse models of many cancer types, has been used for studies of MYC in the cell cycle, genomic instability, transformation and synthetic lethal interactions." (PMID 31350286, 2019). "These risk regions exhibited strong interactions with MYC in their respective cancer cell lines, whereas no risk SNP transcription associated with chr8 transcription was found in normal tissues." (PMID 31309249, 2019). "Since NF-κB has been reported to promote Myc transcription in cancer cells, we hypothesized that NF-κB-driven MYC expression promoted Prmt5 transcription." (PMID 30941147, 2019). "Indeed, overexpression of the MYC oncogene detected in approximately 70% of cancers leads to an upregulation of PD-L1 expression mediated by binding of MYC to the PD-L1 promoter." (PMID 31817953, 2019). "In addition, for a variety of cancer cells (e.g., pancreatic cancer and T cell leukemia), SEs were identified around the MYC gene in cancer cells." (PMID 31824865, 2019). "We propose that reducing the conversion of Trp into Kyn could be an effective strategy to limit the proliferation of MYC-dependent cancer cells." (PMID 31416966, 2019). "The cancer risk-associated SNPs are differentially located on 8q24 in different cancers; for example, rs1561927 in pancreatic cancer locates 455 kb telomeric of PVT1, while rs10088218 in ovarian cancer lies 400 kb 3′ of MYC." (PMID 31309249, 2019). "No effective means currently exists for directly targeting the oncoprotein MYC in cancer." (PMID 31645904, 2019). "MYC plays a central role in multiple oncogenic processes by regulating cell proliferation, apoptosis, and metabolism and has been a key therapeutic target for treatment of many cancers, including HCC." (PMID 31731480, 2019). "It is a key component of oncogenesis and, indeed, MYC is dysregulated in >50% of all cancers." (PMID 31206539, 2019). "Recombinant Omomyc inhibits cancer cell proliferation and affects MYC-mediated transcription." (PMID 31501275, 2019). "From gene profiling analysis, we showed that the most important signal molecules which are critical for most cancer cell or MM survival, such as MYC, E2F, RAS, NFκB, IRF4, mTORC1, and others were significantly down-regulated when Gls1 level was reduced or its activity inhibited." (PMID 31666930, 2019). "MYC amplification is the most common alteration in cancers and is often used as a biomarker." (PMID 30833661, 2019). "In addition, we focus on ncRNAs acting downstream of MYC and pinpoint their contributions to crucial hallmarks of cancer." (PMID 30451365, 2019). "MYC sometimes helps other molecular pathways to promote cancer metastasis." (PMID 30679629, 2019). "As MYC is a Wnt/B-catenin target gene, this suggests a feed forward loop for α6Aβ4 and MYC expressions responsible for the overexpression of the two molecules in cancer cells." (PMID 31877793, 2019). "MYC is overexpressed in human cancer at an unparalleled frequency." (PMID 30902071, 2019). "PVT1 is located in the cancer-related region, chromosome 8q24, upstream of the oncogene MYC." (PMID 30679629, 2019).
cancer (continued). "The MYC oncogene, a potent transcriptional driver of growth-associated gene programs via all three RNA polymerases (Pol I, II, and III), has been implicated in sensitizing MYC-addicted cancer cells to inhibition of Pol I transcription." (PMID 30701204, 2019). "Often, these lncRNAs are deregulated in cancer and promote high MYC levels and activity." (PMID 30451365, 2019). "The function of c-MYC makes it a highly attractive target for anti-cancer therapy." (PMID 31015523, 2019). "Furthermore, bone marrow MSC-conditioned medium has been demonstrated to promote cancer development via upregulation of c-MYC." (PMID 30836996, 2019). "MYC is also thought to be very important in cancer cell apoptosis and differentiation." (PMID 31088567, 2019). "MYC is one of the most commonly activated oncogenes in a broad spectrum of human cancers." (PMID 30247654, 2019). "Thus, MYC plays an ambivalent role as a proliferation and differentiation factor in stem cells, as well as an oncogene in cancer cells." (PMID 30836996, 2019). "We hence evaluated the effects of QN-1 on TNBC cells, demonstrating that it could provoke cell cycle arrest and apoptosis, repress metastasis and inhibit cancer cell growth, which might be ascribed to downregulation of c-MYC expression." (PMID 31584090, 2019). "If so, XBP1s–c-MYC axis will provide a strong feedback loop that establishes a pro-survival pathway in cancer cells that could be targeted at multiple sites for potential therapeutic applications." (PMID 30679434, 2019). "Thus, although MYC is described as one of the most important oncogenes, it is important to realize that there is an extensive, multilayered ncRNA network around MYC, in which intricate crosstalk contributes to hallmarks of cancer." (PMID 30451365, 2019). "However, none of these clinical studies are designed to use cardiac glycosides against cancer types driven by specific oncogene, such as MYC-driven cancers; although the effect of cardiac glycosides on MYC inhibition has been previously reported." (PMID 31196146, 2019). "Overexpression of CCND1 and MYC in cancer is investigated and confirmed." (PMID 34466490, 2019). "In addition, while the expression of the cell cycle progression inhibitor CDKN1A (p21) was decreased in cancer EVs-exposed cells, the expression of the oncogenes MYC and HRAS was increased." (PMID 31200749, 2019). "Interestingly, CRISPRi (CRISPR-inhibition) targeting PVT1 promoter led to enhancement of MYC expression and cancer cell proliferation, while reversal of the interference abolished MYC activity." (PMID 31658672, 2019). "The m6A-modification of the MYC mRNA promotes the association of IGF2BP1 resulting in reduced decay of the MYC transcript and consequently enhanced the expression of this oncogene in cancer cells." (PMID 30371874, 2019). "We compared KAT protein levels before and after proscillaridin A treatment in MYC overexpressing cancer cells (MOLT-4, NALM-6, MYC and RASV12 + MYC transformed fibroblasts) versus low MYC expressing cancer cells (SW48, A549, and RASV12 transformed fibroblasts)." (PMID 31196146, 2019). "Defective regulation of MYC leads to several forms of cancers." (PMID 30871121, 2019). "It is worth further investigating whether CircPVT1 has similar mechanisms to PVT1 in cancer cells, whether CircPVT1 interacts with MYC, and which molecules CircPVT1 can regulate to participate in the downstream signaling pathway of c-Myc." (PMID 31309249, 2019). "In addition to growth control, dMyc/MYC plays a conserved role in upregulating glycolysis in vertebrates and Drosophila during normal development and in cancers." (PMID 31259690, 2019). "Lastly, we discovered potent synergistic interactions between FPP-OmoMYC and docetaxel, doxorubicin and cetuximab which could be implemented for future treatment of MYC-activated cancers." (PMID 30076412, 2019).
cancer (continued). "It is tempting to speculate that this principle could be applied to other non‐MYC‐driven cancers with increased proliferation and transcription." (PMID 31334570, 2019). "Recently, XPO1 inhibition was shown to downregulate MYC expression in several cancer cell lines." (PMID 31752970, 2019). "CD105 shared a common mediator in MYC to induce cancer stemness and EMT traits in ccRCC cells." (PMID 31015843, 2019). "Importantly, the key cancer-drivers/oncogenes MYC, MYB and AR were suppressed by TSPX in a CAD-dependent manner." (PMID 30863497, 2019). "MYC overexpression has been shown to be regulated by BRD proteins in multiple cancer types." (PMID 31288832, 2019). "MYC is a multifunctional oncogenic transcription factor that is frequently overexpressed in cancer." (PMID 30728358, 2019). "Moreover, HCC45 was enriched for targets of several well-known cancer-related transcription factors such as MYC and RUNX1 and were functionally connected as a group (protein–protein interaction network enrichment: P < 1e−16)." (PMID 30626396, 2019). "Given the wide important role of MYC in cancer, a direct MYC inhibitor could be clinically valuable." (PMID 31142021, 2019). "We then explored the genetic landscape of eight out of the nine MYC protein-negative cases for which enough DNA was available by an ultra-deep sequencing analysis targeted on 409 cancer associated genes." (PMID 31748534, 2019). "MAPK8 has been shown to interact with MYC which is frequently observed in numerous human cancers." (PMID 31080457, 2019). "Thus, targeting metabolic pathways modulated by MYC, like fat oxidation, is an intriguing therapeutic opportunity for MYC-driven cancers." (PMID 31142021, 2019). "c-MYC has been well-studied for its role as a proto-oncogene and is often over-expressed in cancer." (PMID 31491003, 2019). "Indeed, the transcription factor MYC plays key roles in oncogenesis and is involved in many cancer networks." (PMID 30688660, 2019). "MYC has long been considered as a promising target for cancer treatment." (PMID 31088567, 2019). "Tissue microarray analysis of 8 primary tumors (lung, colon, rectum, stomach, esophagus, liver, kidney, and mammary gland) indicated a high correlation between PVT1 and c-Myc expression, providing strong evidence for the cooperation of PVT1 and MYC in different human cancers." (PMID 31309249, 2019). "Many human cancers including GBMs demonstrate oncogenic addiction to MYC signaling." (PMID 31754113, 2019). "Notably, cancers driven by MYC amplification were shown to be selectively sensitive to Aurora-A inhibition." (PMID 30177840, 2019). "Alternatively, c-MYC is another essential driver of tumorigenesis and glycolysis in cancer." (PMID 30967773, 2019). "Therefore, the SE controlled genes that include mostly oncogenes in cancer such as MYC, get more affected than other genes in tumor cells." (PMID 31724731, 2019). "Furthermore, KLB down genes were identified, which involved those in cell cycle, DNA replication and packaging, cell division, WNT signaling and other cancer-related pathways such as MYC, VEGF-A and MTOR." (PMID 31695781, 2019). "However, deregulated MYC expression also creates cancer vulnerabilities that can be exploited therapeutically." (PMID 30728358, 2019).
cancer (continued). "MYC is a known proto-oncoprotein that is overexpressed in most cancers." (PMID 31645904, 2019). "Specifically, AURKA and TPX2 together with MYC appear to act as driver genes in MYC-driven cancers." (PMID 30177840, 2019). "While the rs6983267 disease-associated allele augments TCF binding and enhancer activity, whether it differentially impacts MYC gene expression in normal tissues or cancers is still a matter of debate." (PMID 30794691, 2019). "However, some well-known cancer driver genes, such as MYC and COX-2 are common targets of 11 and 7, respectively out of 18 CRC RBPs." (PMID 31440515, 2019). "The addiction of MYC-driven cancers to enhanced ribosome activity has emerged as a vulnerability which might be exploited in cancer therapy." (PMID 30556094, 2019). "How MYC regulates the metabolism of other amino acids in cancer is not fully understood." (PMID 31416966, 2019). "Accordingly, a small peptide representing the BASP1 effector domain could interfere with the proliferation of human cancer cells in which MYC is highly activated." (PMID 31058089, 2019). "Thus, drugs capable of inhibiting nucleolar Pol I-mediated rRNA transcription are emerging as new tools to target MYC-overexpressing cancer." (PMID 29435159, 2018). "Here, we hypothesized that CLK inhibition might function as a novel pre‐mRNA splicing modulation‐based anti‐cancer strategy, especially for MYC‐driven cancers." (PMID 29769258, 2018). "Another metabolic regulator of cancer metabolism is MYC oncogene." (PMID 29495398, 2018). "Because prior studies have revealed that MYC can repress BMAL1 expression in specific cancer cells, we co-transfected the cells with siMyc or scrambled oligonucleotides to determine the extent to which HNF4α repression of Bmal1could be indirect through changes in Myc expression." (PMID 30341289, 2018). "c-MYC transcriptionally regulates the metabolic reprogramming of cancer cells by enhancing glucose uptake, glycolysis, and lactate production, the increase in Nampt expression by c-MYC may lead to the Warburg effects." (PMID 30631755, 2018). "Collectively, our results suggest that the novel CLK inhibitor could have therapeutic benefits, especially for MYC‐driven cancer patients." (PMID 29769258, 2018). "As it is known that Pc and other proteins of the Pc group (PcG) are necessary to MYC auto-repression in Drosophila, Pc downregulation in overt cancers may help sustain high MYC cellular levels, so allowing it to impact many different phenotypic traits." (PMID 30619451, 2018). "MYC is a desired but so far ‘undruggable’ target for cancer treatment." (PMID 30221473, 2018). "Importantly, glutamine is now established as an important nutrient source across numerous cancer types, especially for MYC-driven cancers." (PMID 28748451, 2018). "All these functions of RNA processing make the MYC gene a target for new cancer therapy." (PMID 29495341, 2018). "Increasing knowledge of MYC-coordinated regulation of functions involved in both nucleolar and mitochondrial rRNA transcription and ribogenesis can open new avenues to treat MYC-driven cancer." (PMID 29435159, 2018). "Indeed, in an analysis across >1000 cancer cell lines from the Cancer Cell Line Encyclopedia, a bioribogenesis and protein translation gene set score was found to be highly correlated with MYC expression, with a correlation coefficient of 0.48 at p < 0.0001." (PMID 29799508, 2018). "Furthermore, downregulation of MYC by JQ1 treatment was found to play a partial role in the anti-cancer effects of sunitinib-resistant ccRCC." (PMID 29796168, 2018). "PVT1 was found to be co-amplified in more than 98% of cancers with a MYC copy number increase." (PMID 30217017, 2018). "Further, systematic epigenomic analysis of OIP5-AS1 promoter revealed binding motifs for MYC, NANOG and KLF4 suggesting that OIP5-AS1 could be transactivated by stemness-associated transcription factors in cancer." (PMID 29728583, 2018).